S100B (S100 calcium binding protein B)
Diseases named in the same sentence as S100B in open-access papers (continued):
Sharing a sentence is not in itself a finding about the gene and the disease.
Stroke (continued). "However, the association of serum S100β levels with prognosis in stroke patients who received IVT remains unclear." (PMID 39358745, 2024). "This mini review will address the most common applications of S100B in prognosticating clinical outcome in patients with neurological diseases in general and underline its role in acute diagnostics in patients with traumatic brain injury, spontaneous subarachnoid hemorrhage and stroke." (PMID 37474905, 2023). "The data has also shown that serum S100B levels are closely associated with infarct volume and are positively correlated with the risk of malignant infarction or hemorrhagic transformation after thrombolysis as well as with functional outcome in stroke patients." (PMID 37342100, 2023). "High S100β levels (>0.23 g/L) in blood in ischemic stroke patients are associated with a higher risk of hemorrhagic transformation after thrombolysis treatment, which makes this protein of great interest for informing clinical decision-making after stroke, even though further studies are needed." (PMID 35813155, 2022). "These extracranial origins, such as adipose tissue, skeletal muscle, and chondrocytes, represent a major confounder that limits the utility of S100B as a standalone stroke-specific prognostic biomarker." (PMID 41598337, 2026). "According to recent studies involving stroke patients, both initial and subsequent S100B measurements serve as indicators of functional recovery." (PMID 41598337, 2026). "As an indicator of parenchymal brain damage, S100B is valuable in predicting stroke outcomes and has been shown to correlate with infarct size." (PMID 40142325, 2025). "The determination of S100B can be easily integrated into the routine care of a stroke unit, with a single blood draw 48–72 h after MT in all MT patients." (PMID 39968454, 2025). "NSE is not specific to stroke and can increase in other CNS disorders, and its levels rise more slowly compared to biomarkers like GFAP or S100B, making it less useful for early stroke diagnosis." (PMID 40142325, 2025). "A frequent reason for poor functional outcome at discharge despite low S100B values was post-stroke complications such as infections, especially aspiration pneumonia after endotracheal intubation for MT, or exacerbation of pre-existing disorders." (PMID 39968454, 2025). "Future research should focus on combining NSE with other biomarkers (e.g., GFAP, S100B, or inflammatory markers) to improve stroke diagnosis and prognosis, as well as establishing standardized NSE cutoff values for clinical applications." (PMID 40142325, 2025). "Two patients suffered early recurrent strokes, which occurred after day 2 (and therewith after the first follow-up imaging used for evaluation of the infarct volume and the S100B collection on day 2), of whom one patient suffered additional epileptic seizures." (PMID 39968454, 2025). "Several studies have confirmed these mechanisms and investigated stroke biomarkers, such as IL-6, S100B, NSE, D-Dimer and GFAP in T2DM populations, demonstrating their relevance to stroke risk." (PMID 41150802, 2025). "Both GFAP and S100B serve as promising biomarkers for assessing the severity and prognosis of stroke." (PMID 40863995, 2025). "NETs can further activate thrombotic processes, emphasizing the dual role of S100b in both innate immunity and coagulation during stroke." (PMID 41311551, 2025). "While there are several other markers of brain injury, this study demonstrated that S100B, GFAP and NSE have potential for use as biomarkers in the development of prediabetes-associated stroke events." (PMID 41296388, 2025). "For instance, S100B, a protein detectable in stroke patients, lacks sufficient specificity due to its expression in healthy individuals and in other neurological conditions." (PMID 41348969, 2025).
Stroke (continued). "Clinical studies have demonstrated elevated NSE levels in both cerebrospinal fluid and peripheral blood shortly after stroke onset,while increased S-100B protein concentrations have been consistently observed in cerebrospinal fluid of stroke patients." (PMID 40832150, 2025). "In our research, PTI mice exhibited increased levels of stroke-related markers such as S100B, NT-pro BNP, and GFAP, compared to the Con mice, which is typically observed during IS." (PMID 40688396, 2025). "Compared with serum NSE, S100-β at 48 h of stroke onset had a higher predictive value for AIS prognosis." (PMID 39669377, 2024). "In their study conducted on 42 patients with ischemic stroke, they measured S100B levels on day 3 after the stroke." (PMID 38248781, 2024). "The MMX value obtained by combining the results of four different markers (MMP-9, BNP, S100B, and D-dimer) was significantly higher in stroke patients compared to non-stroke patients." (PMID 39001884, 2024). "This prospective observational study suggests that serum NSE on admission and S100-β at 48 h of stroke onset serve as independent prognostic biomarkers." (PMID 39669377, 2024). "Stroke severity measured with the NIHSS was positively correlated with S100B levels (r = 0.45, p ≤ 0.05) in the study with moderate predictive value." (PMID 39091977, 2024). "These properties, further supported by clinical studies, make S100B an excellent marker for stroke severity regarding active metabolic responses." (PMID 38248781, 2024). "Studies have previously demonstrated altered expression of miR-602 and S100B in patients with stroke." (PMID 39001884, 2024). "S100B is also included in the Triage® Stroke Panel, which is a rapid fluorescence immunoassay for quantitative measurement of BNP, fibrin degradation products containing D-dimer, MMP-9 and S100B in whole samples blood or plasma." (PMID 39001884, 2024). "Serum NSE and S100-β levels were highest in patients with an unfavorable prognosis on admission and at 48 h of stroke onset, respectively." (PMID 39669377, 2024). "The heterogeneity in stroke lateralization in the prognostic function (favorable outcome) of S100β was observed (Pinteraction < 0.001)." (PMID 39358745, 2024). "In patients with ischemic stroke, peak levels of S100B were most often observed on day 3 or 4 after the stroke (during the formation of cytotoxic edema), whereas in patients with TBI, peak levels were observed on day 1 or 2 after the injury." (PMID 38248781, 2024). "A study of 188 AIS patients and 90 stroke mimics reported on a biomarker panel including IL-6, S100B, and MMP-9 which was incorporated in a clinical data assessment (age, AF, Face-Arm-Speech-Test results)." (PMID 39091977, 2024). "Elevated levels of S100-β on admission and NSE 48 h after stroke onset were found to be associated with END events and poor prognosis." (PMID 39669377, 2024). "Microglial S100B expression has also been found to increase with time, starting 1–3 days after middle cerebral artery occlusion in a mouse model for stroke (MCAO), and reaching a peak after five days and then persisting up to 14 days." (PMID 39001884, 2024). "A biomarker panel examined among 89 patients with stroke and 38 HC consisting of BNP, D-dimer, MMP-9, and S100B, and a derived multimarker index, showed higher values in stroke patients compared to HC." (PMID 39091977, 2024). "The present study showed that serum S100β levels 24 h after IVT were independently associated with HT, infarct volume, and prognosis in stroke patients who received IVT." (PMID 39358745, 2024). "S100β levels in the cerebrospinal fluid of patients with IS are also positively correlated with stroke severity." (PMID 39669376, 2024). "It has been reported that the improvement in stroke severity is associated with neuroplasticity, which, in turn, relates to VCAM-1, MMP-9, S100β, and vWF." (PMID 39599732, 2024).
Stroke (continued). "Due to damage to brain tissue and the blood–brain barrier in patients with stroke, S100β is released and enters the bloodstream, resulting in abnormally high levels of S100β in the blood." (PMID 39358745, 2024). "In the current study, it is reasonable to expect elevated serum NSE and S100-β levels in stroke patients compared with controls." (PMID 39669377, 2024). "Serum NSE and S100-β levels on admission and at 24 and 48 h after stroke onset were measured using electrochemiluminescence immunoassays." (PMID 39669377, 2024). "It has been demonstrated that NSE and S100-β are highly sensitive quantitative indicators that increase neuronal injuries such as craniocerebral injury, stroke, cerebral hemorrhage, and cardiac arrest." (PMID 39669377, 2024). "For instance, S100B, a protein released bydamaged brain cells, has been found to be elevated in stroke patients." (PMID 39430040, 2023). "Thus, serum S100B levels may be used as a promising marker to identify patients at increased risk of specific early neurological complications like hemorrhagic transformation after stroke and as an indicator of cerebral damage and functional outcome." (PMID 37342100, 2023). "Measuring S100B levels in the bloodstreamcan help determine the severity and prognosis of the stroke." (PMID 39430040, 2023). "In the field of cardiac surgery, previous studies have shown that S100B correlates with injured volume and can predict stroke." (PMID 36747206, 2023). "Actually, brain-derived markers, particularly neurofilament light chain, tau protein, S100b, in post-stroke patients have yielded promising results." (PMID 37719764, 2023). "In another study by Harpaz, an SPR chip was designed and used in a novel point-of-care SPR system for the detection of the stroke biomarkers NT-proBNP and S100β in water and plasma samples." (PMID 37366997, 2023). "NT-proBNP and S100β were detected in a range of clinically relevant concentrations for stroke, from 0.1 ng/mL to 10 ng/mL." (PMID 37366997, 2023). "Recently, S100b has been proposed as a surrogate marker to monitor the stroke response after endovascular treatment." (PMID 37719764, 2023). "Although S100B can be considered a useful biomarker in the acute phase after stroke to evaluate the damage of the NVU and astroglial cells, further investigations to understand its role in SDNG following stroke are needed." (PMID 37719764, 2023). "In another study, HFABP was compared with S100b in the diagnosis of stroke and in the prediction of long-term clinical outcomes showing a sensitivity of 59.5%, specificity of 79.5% and AUC 0.71." (PMID 37511304, 2023). "S100B showed a sensitivity of 55% and specificity of 64% in differentiating between stroke and stroke mimics for cut-off values <= to 130 ng/L." (PMID 37511304, 2023). "S100B was found to be correlated with the severity of stroke, defined by neurological symptoms and infarct volume, and patient functional outcome at discharge in multiple human studies as measured by the modified Rankin Scale." (PMID 37446092, 2023). "NSE and S100β were also included in the presented predictive model to evaluate the prognosis of patients with stroke." (PMID 37612344, 2023). "Previous studies have reported that increased levels of NSE and S100B are positively correlated with poor outcomes of stroke patients, which is consistent with our findings." (PMID 37612344, 2023). "Results show a higher circulating level of S100β in obese mice subjected to stroke than that measured in animals of the control ND group." (PMID 35624723, 2022). "In the present study, we describe the temporal pattern of tau, NFL, GFAp, NSE and S100B in the blood after stroke following large vessel occlusions and embolectomy in the anterior circulation of the brain." (PMID 33723754, 2022). "S100B in peripheral blood is a sensitive marker of blood–brain barrier dysfunction and ischemic brain injury and is also a predictor of stroke prognosis." (PMID 36504682, 2022).
Stroke (continued). "In this study, we investigated the use of the brain damage biomarkers tau, NFL, NSE, GFAp, and S100B to understand the progression of nervous tissue damage and their relationship to outcome in such stroke after endovascular treatment." (PMID 33723754, 2022). "Although GFAP is a more sensitive biomarker for small cerebral ischemic injury and minor stroke in comparison with S100B, its delayed increase following mild ischemic injuries makes its clinical usage as a diagnostic tool limited." (PMID 35207321, 2022). "A clinical trial targeted reducing secretion of S100β from astrocytes in ischaemic stroke patients produced a favourable trend in reduction of the National Institutes of Health Stroke Scale (NIHSS) that should be confirmed in a future clinical trial." (PMID 33924191, 2021). "Arundic acid (ONO-2506), which reduces the synthesis of S100β in astrocytes, has been shown to decrease stroke volume and improve functional outcomes." (PMID 33924191, 2021). "In another study, a biomarker panel composed of sRAGE and S100B was able to distinguish acute IS vs. HS and to improve stroke diagnosis when compared with the biomarkers alone." (PMID 34440560, 2021). "We searched the MEDLINE database for “DAMPs” or “RAGE” or “S100B” and “traumatic brain injury” or “subarachnoid hemorrhage” or “stroke”." (PMID 33670976, 2021). "In the course of cerebral ischemic stroke and TIA, an increase in concentration of S100β protein in CSF was detected within about 9 h from the stroke symptoms onset." (PMID 31701356, 2020). "S100β protein levels in CSF are differentiated in various types of stroke, being higher in cardioembolic stroke, compared to the small-vessel disease, and they correlate with an infarct volume." (PMID 31701356, 2020). "The functional outcomes were evaluated 6 months after stroke by the Barthel index, which was correlated with age and the serum levels of sTREM-1 and S100B." (PMID 33375339, 2020). "The serum levels of sTREM-1, TNFα, IL-6, and S100B were correlated with the stroke volume and NIHSS, after acute ischemic stroke." (PMID 33375339, 2020). "The CSF S100β levels positively correlate with stroke severity, assessed with the NIHSS score on admission, also with an infarct volume, and with patients’ outcome according to the mRS score after three months from the ischemic infarct onset." (PMID 31701356, 2020). "NSE, IL-6, NT-proBNP, S-100b, hsCRP levels, and hsTroponin showed significantly lower circulating levels in stroke patients with previous TIA ≤ 24 h." (PMID 33192985, 2020). "We found that the serum levels of sTREM-1, TNFα, IL-6, and S100B were correlated with the severity of stroke, as evaluated by TOAST and NIHSS after acute ischemic stroke." (PMID 33375339, 2020). "Previous studies showed increases of MBP antigens (along with neuron-specific enolase and S100-β) in the serum of stroke patients in the first 24 h after stroke." (PMID 32719588, 2020). "NT-proBNP and S100β were chosen as the two stroke biomarkers candidates as they have been extensively studied and have shown great diagnostic accuracy." (PMID 31163612, 2019). "S100B is a useful neurobiochemical marker of brain damage such as in circulatory arrest, stroke, traumatic brain injury and Alzheimer disease." (PMID 31263455, 2019). "This study shows the use of a novel SPR module (PhotonicSys SPR H5) that is tested for the detection of the stroke biomarkers NT-proBNP and S100β." (PMID 31163612, 2019). "NT-proBNP and S100β were detected in a range of concentrations for stroke, from 0.25 ng/mL to 10 ng/mL." (PMID 31163612, 2019). "NT-proBNP and S100β were detected in a range of concentrations for stroke, from 0.1 ng/mL to 10 ng/mL." (PMID 31163612, 2019). "In this study, a functionalized specific SPR chip was designed and used in a novel point-of-care SPR module (PhotonicSys SPR H5) for the detection of the stroke biomarkers NT-proBNP and S100β." (PMID 31163612, 2019).
Stroke (continued). "S100b protein is recommended for the rapid detection of neuronal damage resulting from traumatic brain injury, stroke, or subarachnoid hemorrhage, and synthetic cannabinoid use." (PMID 30396875, 2019). "At the onset of any neurodegenerative disorders such as Alzheimer’s, Down’s syndrome, trauma, brain injury, myocardial infarction and stroke, there is an increase in the concentration of S100β proteins which serves as a biomarker for clinical purposes." (PMID 30069254, 2018). "In stroke, S100B is released in the cerebrospinal fluid at the beginning of the ischemic period and enters the bloodstream, where the levels peak within 24–120 h after ischemia." (PMID 30245755, 2018). "Other biomarker elevations have been associated with stroke such as Brain Natriuretic Peptide (BNP), D-dimer and S-100β protein." (PMID 27247610, 2016). "An increase of biochemical markers such as BNP, D-Dimers, MMP-9, and S100β tested with a Triage Stroke Panel (>4) was correlated with mortality at 120 days from stroke onset." (PMID 27247610, 2016). "In ischemic stroke, serum ficolin-3 levels are inversely correlated with the severity of stroke indicated by the National Institute of Health stroke scale on admission and the concentrations of S100b, an indicator of the size of cerebral infarct." (PMID 26627059, 2015). "Isoflurane post-treatment also reduced brain infarct volumes and plasma S100B 3 days after the injection of 5 mg clots and improved neurological deficit scores after the stroke." (PMID 26645542, 2015). "An algorithm that combined the value of four protein markers (matrix metalloproteinase 9, D-dimer, S100b, and B-type natriuretic peptide) was found to have an AUC of 0.69 for differentiating stroke from mimic." (PMID 26076478, 2015). "Our results showed that embolic stroke increased plasma S100B and isoflurane post-treatment reduced this increase." (PMID 26645542, 2015). "The pattern of reactive astrogliosis observed in animals and human studies explains the plasma S100β protein temporal profiles in stroke patients, with plasma S100β protein peaking later than in TBI patients." (PMID 25029344, 2014). "S100B was sensitive to predict coma and severe brain injury (stroke, postanoxic encephalopathy, and head trauma) but more frequent measurements over a longer period than four days were probably necessary to diagnose delirium, which fluctuated over time." (PMID 24883321, 2014). "Several case-control studies showed that blood levels of S100B, NSE and GFAP are elevated in acute stroke, and are associated with poor stroke outcome." (PMID 23497639, 2013). "ADMA levels at the time points 12 and 24 hours, 3 and 7 days, IL-6 levels at 6, 12 and 24 hours, and S100B levels at all time points were higher in stroke patients than in controls (P <0.05)." (PMID 23158556, 2012). "Elevated levels of S100B had been observed after head trauma and stroke and can reflect a brain injury or dysfunction of blood-brain barrier." (PMID 21810220, 2011). "Significant univariate associations were found between age, stroke syndrome, neurologic impairment (NIHSS Score), disability (Modified Barthel Index score), lesion area, hs-CRP and serum concentration of S100B." (PMID 21034449, 2010). "In stroke, global hypoxia and traumatic brain injury a positive correlation between S100B and cognitive outcome has been established." (PMID 19473521, 2009). "S100B is more indicative of a past or ongoing stroke rather than a predictive marker for future stroke risk." (PMID 41296388, 2025). "Additionally, sex differences in inflammatory markers such as IL-6, CRP, and S100B were observed, with these biomarkers being more elevated in female stroke patients." (PMID 40356948, 2025). "IL-6, NSE, S100B, and miR-124 usually increase within 3–12 h of a stroke." (PMID 40949500, 2025). "Finally, serum NSE on admission and S100-β level at 48 h of stroke onset were independent predictors of functional recovery at 3 months in patients with AIS." (PMID 39669377, 2024).